C5 (complement C5)
Description:
Precursor of the C5a anaphylatoxin and complement C5b components of the complement pathways, which consist in a cascade of proteins that leads to phagocytosis and breakdown of pathogens and signaling that strengthens the adaptive immune system. Activated downstream of classical, alternative, lectin and GZMK complement pathways. [Complement C5b]: Component of the membrane attack complex (MAC), a multiprotein complex activated by the complement cascade, which inserts into a target cell membrane and forms a pore, leading to target cell membrane rupture and cell lysis. Complement C5b is generated following cleavage by C5 convertase and initiates formation of the MAC complex: C5b binds sequentially C6, C7, C8 and multiple copies of the pore-forming subunit C9. During MAC complex assembly, the C5b6 subcomplex, composed of complement C5b and C6, associates with the outer leaflet of target cell membrane, reducing the energy for membrane bending. [C5a anaphylatoxin]: Mediator of local inflammatory process released following cleavage by C5 convertase. Acts by binding to its receptor (C5AR1 or C5AR2), activating G protein-coupled receptor signaling and inducing a variety of responses including intracellular calcium release, contraction of smooth muscle, increased vascular permeability, and histamine release from mast cells and basophilic leukocytes. C5a is also a potent chemokine which stimulates the locomotion of polymorphonuclear leukocytes and directs their migration toward sites of inflammation.
Synonyms: CPAMD4; C5a; C5b; C5D; ECLZB
Tractability: Small molecule: a structure with a bound ligand is known; a high-quality ligand is known; it has a binding pocket of medium quality. Antibody: an approved drug acts on it; UniProt places it where antibodies can reach, with high confidence; its Gene Ontology location is reachable by antibodies, with high confidence; UniProt predicts a signal peptide or a membrane-spanning region. PROTAC: ubiquitination databases record sites on it; its protein half-life has been measured; a small molecule that binds it is known. Other modalities: an approved drug acts on it.
Target class: Secreted protein
Gene: Protein-coding gene on chromosome 9 (120,932,987 to 121,075,195, reverse strand). Ensembl gene ENSG00000106804.
Subcellular location: Secreted; Secreted (Complement C5b); Target cell membrane; Secreted (C5a anaphylatoxin)
Pathways (Reactome):
Immune System: Activation of C3 and C5; Regulation of Complement cascade; Terminal pathway of complement
Signal Transduction: G alpha (i) signalling events; Peptide ligand-binding receptors
Gene Ontology:
Molecular function: protein binding; chemokine activity; signaling receptor binding; endopeptidase inhibitor activity; G protein-coupled receptor binding
Biological process: complement activation, GZMK pathway; negative regulation of macrophage chemotaxis; positive regulation of chemokine production; positive regulation of vascular endothelial growth factor production; cell surface receptor signaling pathway; chemotaxis; G protein-coupled receptor signaling pathway; inflammatory response; cell chemotaxis; cell migration; complement activation; positive regulation of angiogenesis; regulation of chemotaxis; response to other organism
Cellular component: extracellular exosome; extracellular region; membrane attack complex
Genetic constraint (gnomAD): Loss-of-function variants: 80 observed, 123.74 expected, observed/expected ratio (o/e) 0.65, 90% interval 0.54 to 0.78. The upper end of that interval is the gene's LOEUF score, 0.78, which puts it in group 3 of 6, group 1 being the genes least tolerant of losing a copy. Missense variants: 1,155 observed, 1,398 expected, observed/expected ratio (o/e) 0.83, 90% interval 0.79 to 0.87. Synonymous variants: 429 observed, 504.39 expected, observed/expected ratio (o/e) 0.85, 90% interval 0.79 to 0.92.
Homologues: Orthologues: chimpanzee C5 (99% identical), macaque C5 (96% identical), rabbit C5 (84% identical), guinea pig C5 (82% identical), pig C5 (81% identical), dog C5 (81% identical), rat C5 (80% identical), mouse Hc (78% identical), zebrafish c5 (38% identical), tropical clawed frog c5 (33% identical), Drosophila melanogaster Tep2 (17% identical), Caenorhabditis elegans tep-1 (16% identical), and 5 more. Paralogues in human: C3 (28% identical), C4B (25% identical), C4A (25% identical), A2M (18% identical), CPAMD8 (18% identical), PZP (18% identical), A2ML1 (18% identical), CD109 (17% identical).
Diseases named in the same sentence as C5 in open-access papers:
C5 is named in the same sentence as 301 diseases in open-access papers, as found by Europe PMC text mining. Sharing a sentence is not in itself a finding about the gene and the disease. The quoted sentences say what the papers report.
paroxysmal nocturnal hemoglobinuria (101 papers, 2007 to 2026). Paroxysmal nocturnal hemoglobinuria (PNH) is an acquired clonal hematopoietic stem cell disorder characterized by corpuscular hemolytic anemia, bone marrow failure and frequent thrombotic events. "This C5 inhibitor has been evaluated for paroxysmal nocturnal hemoglobinuria (PNH), CD55-deficient protein-losing enteropathy, and CHAPLE disease." (PMID 38140161, 2023). "Several complement antibody-therapeutics are currently under development, but only Eculizumab (anti-C5) is approved to treat alternative pathway-associated disorders, aHUS and paroxysmal nocturnal hemoglobinuria (PNH)." (PMID 24797388, 2014). "We performed an analysis of C5 gene for his poor response to eculizumab, because its single missense heterozygous mutation causes a poor response to eculizumab in Japanese patients with paroxysmal nocturnal hemoglobinuria (PNH)." (PMID 32571244, 2020). "C5 blocker eculizumab is the first-in-class complement inhibitor that has been approved for paroxysmal nocturnal hemoglobinuria (PNH), aHUS, myasthenia gravis, and neuromyelitis optica." (PMID 40406401, 2025). "Therapeutic inhibition of complement, especially at the level of C5 using agents such as eculizumab, has been successfully used to treat conditions such as paroxysmal nocturnal hemoglobinuria (PNH) and atypical hemolytic uremic syndrome (aHUS)." (PMID 41157595, 2025). "The humanized monoclonal antibody eculizumab has been used as a C5 inhibitor in patients with paroxysmal nocturnal hemoglobinuria, with promising results and significant improvement." (PMID 40565360, 2025). "Eculizumab, a humanized anti-C5 antibody, is the first drug to prevent complement-mediated intravascular hemolysis in paroxysmal nocturnal hemoglobinuria (PNH) and atypical hemolytic uremic syndrome (aHUS)." (PMID 41511330, 2025). "A novel complement C3 inhibitor, pegcetacoplan, was recently approved to treat paroxysmal nocturnal hemoglobinuria, a condition commonly treated with complement C5 inhibitors." (PMID 40023814, 2025). "In several studies, patients with paroxysmal nocturnal hemoglobinuria had their treatment switched from eculizumab to Ravulizumab, another complement C5 inhibitor." (PMID 40565360, 2025). "The addition of Danicopan alongside C5 inhibitors in patients with paroxysmal nocturnal hemoglobinuria further improved the outcomes and its benefits were confirmed by other studies." (PMID 40565360, 2025). "In the kidney, C5 blockade has revolutionized the treatment of aHUS and paroxysmal nocturnal hemoglobinuria (PNH), both diseases where MAC‐mediated endothelial cell damage represents a crucial therapeutic target." (PMID 41189475, 2025). "Complement factor 5 (C5) inhibitors for paroxysmal nocturnal hemoglobinuria (PNH) may cause iron overload due to residual intravascular hemolysis (IVH) and emergent extravascular hemolysis (EVH)." (PMID 41155315, 2025). "Eculizumab, a monoclonal antibody that blocks C5 activation, has demonstrated potential in reducing complement-mediated damage in conditions like paroxysmal nocturnal hemoglobinuria (PNH)." (PMID 40119227, 2025). "C5 inhibitors have been approved for the treatment of diseases of complement overactivation, including paroxysmal nocturnal hemoglobinuria, atypical hemolytic uremic syndrome, and vasculitis." (PMID 38601164, 2024). "Eculizumab is an antibody that binds to complement C5, inhibiting the cleavage of C5 to C5a and C5b, and is approved for the treatment of paroxysmal nocturnal hemoglobinuria." (PMID 39409001, 2024). "Eculizumab is a humanized IgG2–G4-kappa antibody that targets complement 5 (C5), previously established as therapy for disorders such as hemolytic uremic syndrome and paroxysmal nocturnal hemoglobinuria." (PMID 38140161, 2023).
paroxysmal nocturnal hemoglobinuria (continued). "The 2007 FDA approval of Eculizumab (Soliris, Alexion Pharmaceuticals), an anti-C5 monoclonal antibody, for the treatment of Paroxysmal Nocturnal Hemoglobinuria (PNH), presented a significant milestone in the field of complement therapeutics." (PMID 36148231, 2022). "The inhibition of activated complement has already demonstrated notable success in clinical practice, for example, C3 and/or C5 inhibitors for paroxysmal nocturnal hemoglobinuria (PNH) or targeting C1s in cold agglutination disease." (PMID 36291163, 2022). "This group included 10 patients on complement inhibitors: 7 paroxysmal nocturnal hemoglobinuria on C5 inhibitor eculizumab/ravulizumab (N = 6) or on oral factor B inhibitor (N = 1), and 3 cold agglutinin disease on C1s inhibitor sutimlimab." (PMID 35634287, 2022). "Eculizumab and its long-lasting form, ravulizumab, are monoclonal antibodies that bind to C5 and inhibit its cleavage by C5a, both approved for paroxysmal nocturnal hemoglobinuria." (PMID 34944611, 2021). "In the past decades, as the first FDA-approved complement inhibitor, eculizumab (C5 inhibitor) is used to treat the hemolytic disorder, paroxysmal nocturnal hemoglobinuria (PNH), which remarks an important milestone in complement drug discovery." (PMID 34368372, 2021). "One patient with paroxysmal nocturnal hemoglobinuria received the monoclonal antibody Eculizumab, which inhibits C5-mediated terminal complement activation." (PMID 34441027, 2021). "Initially approved to treat paroxysmal nocturnal hemoglobinuria and more recently approved for myasthenia gravis and AQp4-IgG positive neuromyelitis optica, anti-C5 acts systemically to inhibit complement activation at the level of the C5-convretase." (PMID 34671342, 2021). "On the other hand, eculizumab, which is a humanized mAb against C5 complement protein, originally used to treat paroxysmal nocturnal hemoglobinuria (PNH) is an approved treatment option for generalized AChR antibody-positive MG." (PMID 33530460, 2021). "A few of them received FDA approval for inflammatory indications including eculizumab targeting the terminal complement pathway starting from C5, which is currently used for the treatment of paroxysmal nocturnal hemoglobinuria (PNH)." (PMID 30949180, 2019). "Eculizumab, a humanized anti-C5 antibody, is the lead anti-complement drug but to date has only been approved for two rare disorders, paroxysmal nocturnal hemoglobinuria (PNH) and atypical hemolytic uremic syndrome (aHUS) and recently for Myasthenia Gravis." (PMID 30886620, 2019). "This is well-known in paroxysmal nocturnal hemoglobinuria (PNH) in which the eculizumab treatment—a human monoclonal antibody against the C5 component of complement that blocks the terminal complement pathway—facilitates abrogate intravascular hemolysis." (PMID 31766155, 2019). "Anti-C5 antibody targets the common terminal portion of the complement cascade that generate the terminal complex C5b-9 and has a renal-protective effect in paroxysmal nocturnal hemoglobinuria." (PMID 31662004, 2019). "More specifically, the humanized anti-C5 antibody (eculizumab) is widely used to treat atypical hemolytic uremic syndrome and paroxysmal nocturnal hemoglobinuria." (PMID 29616034, 2018). "This antibody acts against C5 and is currently used to treat paroxysmal nocturnal hemoglobinuria, which is characterized by chronic C5 activation." (PMID 29894483, 2018). "Anti-C5 monoclonal antibody eculizumab is used as a therapeutic for paroxysmal nocturnal hemoglobinuria." (PMID 29483907, 2018). "The complement component 5 (C5)-binding antibody eculizumab is used to treat patients with paroxysmal nocturnal hemoglobinuria (PNH) and atypical haemolytic uremic syndrome (aHUS)." (PMID 27509843, 2016).
paroxysmal nocturnal hemoglobinuria (continued). "PMX53 is not in clinical development, but an antibody that inactivates complement C5 has been approved for use against two rare diseases, paroxysmal nocturnal hemoglobinuria and atypical hemolytic uremic syndrome." (PMID 27105526, 2016). "Eculizumab, an anti-C5 antibody, is effective in limiting complement activation in patients with paroxysmal nocturnal hemoglobinuria, aHUS, or refractory IgA nephropathy in some case reports." (PMID 29043138, 2016). "In the present, replacement therapy of C1-inhibitor is also another established treatment for hereditary angioedema in addition to anti-C5 antibodies for C-dependent hemolytic anemia in patients with paroxysmal nocturnal hemoglobinuria, respectively." (PMID 22851928, 2012). "Infusion of the humanized, monoclonal anti-C5 antibody eculizumab has recently been documented as a powerful therapeutic measure in paroxysmal nocturnal hemoglobinuria." (PMID 17891600, 2007). "Considering the involvement of the dysregulated complement cascade in severe COVID-19 complications, ravulizumab (Alexion Pharmaceuticals), a humanized IgG2/4 directed against C5, marketed for treatment of paroxysmal nocturnal hemoglobinuria, was evaluated in Phase 3 (NCT04369469)." (PMID 33668613, 2021). "Eculizumab, a complement C5 inhibitor used for the treatment of paroxysmal nocturnal hemoglobinuria, has demonstrated some efficacy in delaying disease progression, with the addition of treponistil becoming the mainstay of therapy for patients who develop systemic disease." (PMID 33957947, 2021). "Interestingly, in 2007 the US Food and Drug Administration approved anti-C5 blocking therapies for treating paroxysmal nocturnal hemoglobinuria and more recently for atypical hemolytic uremic syndrome." (PMID 32244854, 2020). "There is an unmet clinical need for effective treatment of paroxysmal nocturnal hemoglobinuria (PNH) in pregnancy for patients with inadequate response to C5 inhibitors." (PMID 41268092, 2025). "Paroxysmal nocturnal hemoglobinuria (PNH) is a rare blood disorder with C5 inhibitors (C5i), eculizumab and ravulizumab, being part of current treatment options." (PMID 40827257, 2025). "In 2007, eculizumab was the first anti-C5 inhibitor to receive FDA approval for the treatment of paroxysmal nocturnal hemoglobinuria (PNH), followed by atypical hemolytic uremic syndrome (aHUS)." (PMID 38671903, 2024). "The other five cases were associated with acquired deficiency due to treatment for Paroxysmal nocturnal hemoglobinuria (PNH) using monoclonal antibodies treatment (eculizumab or ravulizumab) against the C5 complement component (anti-C5 mAb)." (PMID 39770731, 2024). "Paroxysmal nocturnal hemoglobinuria (PNH), a rare acquired hematologic disorder, can be treated with C5 inhibitors (C5i) such as eculizumab or ravulizumab." (PMID 37092521, 2023). "More than half of patients with paroxysmal nocturnal hemoglobinuria (PNH) treated with complement fraction C5 inhibitors experience residual anemia and hemolysis." (PMID 36532073, 2022). "C5 inhibition has been used clinically for 15 years in the setting of paroxysmal nocturnal hemoglobinuria (PNH), a rare blood disorder characterized by complement-dependent hemolysis." (PMID 33374356, 2020). "Eculizumab, a monoclonal anti-C5 antibody, has been reported to be effective in controlling thrombotic microangiopathy and improving renal function, and is used in clinical practice to treat paroxysmal nocturnal hemoglobinuria (PNH) and atypical hemolytic-uremic syndrome (aHUS)." (PMID 29466390, 2018). "Eculizumab, an anti-complement C5 monoclonal antibody, is the current standard of care for paroxysmal nocturnal hemoglobinuria (PNH) and atypical hemolytic uremic syndrome (aHUS)." (PMID 28439081, 2017). "C5 blockade by eculizumab prevents complement-mediated intravascular hemolysis in paroxysmal nocturnal hemoglobinuria (PNH)." (PMID 28629435, 2017).